INS (insulin)
Diseases named in the same sentence as INS in open-access papers (continued):
Sharing a sentence is not in itself a finding about the gene and the disease.
diabetes (continued). "However, after one century from the discovery of insulin and 98 years from the discovery of glucagon, we should recognize that also this latter hormone plays a critical role in diabetes pathophysiology." (PMID 34572493, 2021). "Electrochemical insulin sensors can be considered as a novel approach for diabetes diagnosis." (PMID 34372300, 2021). "However, given that all patients in the study cohort were prescribed insulin for glycemic control, an advanced stage of diabetes can be inferred." (PMID 33947391, 2021). "Examples of in utero exposures include mother’s diabetes or hypertensive disorder during pregnancy, which can influence glucose metabolism and insulin sensitivity in the prematurely born individual through shared genetic susceptibility or developmental programming." (PMID 34972182, 2021). "Our results indicate that the proposed approach is feasible for more reliable BG forecasting that might improve the performance of the artificial pancreas and insulin infusion system for T1D diabetes management." (PMID 33726723, 2021). "As bone tenacity is determined primarily by the unmineralized matrix, it is conceivable that the observed insulin benefit to femoral tenacity is due to an increase in the femoral collagen content promoted by insulin in this model of experimental diabetes by our group." (PMID 34440530, 2021). "Moreover, the administration of nitrate or nitrite reduces the accumulation of fat in adipose tissues and improves insulin signaling in mouse models of diabetes and metabolic syndrome." (PMID 34266472, 2021). "Other conditions that might alter the results of this research were the duration of diabetes and plasma insulin level." (PMID 33653396, 2021). "To this end, we tested whether the anti-NP primary immune response induces diabetes symptoms due to binding to insulin." (PMID 34434193, 2021). "Previous studies reported that exercise can increase insulin sensitivity in people with diabetes and promote the production of endothelium-dependent vasodilator nitric oxide, thus improving endothelial and microvascular function and promoting metabolism in the lower extremities." (PMID 34900954, 2021). "Transient activation of O-GlcNAc signaling is cytoprotective but its sustained elevation that is found in diabetes is involved in impaired mitochondrial function, abnormal insulin metabolic signaling, endothelial dysfunction, myocardial excitation–contraction coupling, and cardiomyocyte apoptosis." (PMID 34205870, 2021). "Consistent with this notion, a comparison of those with normal glucose tolerance, impaired glucose tolerance, and type 2 diabetes found that insulin sensitivity declined between normal and impaired glucose tolerance whereas insulin secretion was decreased from impaired glucose tolerance to diabetes." (PMID 34206745, 2021). "Insulin remains the recommended therapy for most patients with diabetes during hospitalization." (PMID 34842544, 2021). "Previous research reported that insulin and diabetes can alter cholesterol metabolism in the brain." (PMID 34054500, 2021). "The dysregulation of intrinsic (intracellular regulation of glucagon/insulin biosynthesis and secretion) and extrinsic (external neurohormonal input that regulates biosynthesis and secretion) mechanisms of glucagon/insulin physiology contribute to the pathogenesis of diabetes." (PMID 35002748, 2021). "In addition, chicory treatment led to an increase in insulin level in the early stage of diabetes, pointing toward the insulin-sensitizing action of chicory." (PMID 33572627, 2021). "The study cohort consists of 25,186 patients (mean age = 63.0, interquartile range [IQR] of age = 15.1 years, male = 50.4%, type 1 diabetes mellitus = 7.37%, baseline diabetes duration = 2.84 ± 2.54 years, total duration = 69,332 patient-years, daily insulin dosage: 20.2 ± 12.6 units)." (PMID 33947391, 2021).
diabetes (continued). "The Global Diabetes Compact was launched by the World Health Organization in April 2021 with one of its important goals to increase the accessibility and affordability of life-saving medicine—insulin." (PMID 34336550, 2021). "Serum UA level will increase with an increased insulin level in patients with diabetes." (PMID 34177370, 2021). "Five quality of life (QoL) domains are particularly important to patients with type 2 diabetes (T2D) using basal insulin—sense of physical well-being, sense of safety regarding hypoglycemia, sense of diabetes as burdensome, feelings of freedom and flexibility, and sleep quality." (PMID 33550540, 2021). "Diabetes mellitus (DM), one of the most common metabolic diseases, is caused by a lack of insulin (T1DM) or reduced sensitivity and increased insulin resistance (T2DM)." (PMID 34393784, 2021). "Meanwhile, ceramida may activate PKCs and inhibit insulin metabolic Akt/PKB signaling (Akt: phosphoinositide dependent kinase), downregulating glucose transporter 4 (GLUT4) translocation and insulin-stimulated glucose uptake in heart tissue with diabetes." (PMID 34769060, 2021). "In particular, Type 1 DM (T1DM), once referred to as juvenile diabetes or insulin-dependent diabetes mellitus, is a chronic autoimmune condition in which the pancreas is not able to produce enough insulin due to the loss of beta cells." (PMID 34501572, 2021). "One trigger for distress in people with diabetes could be the perceived limitations in quality of life, for example, due to high daily frequency of insulin injections and glucose tests." (PMID 33836823, 2021). "Likewise, thymoquinone also prevented mature male Wistar rats from streptozotocin‐induced diabetes via decreasing blood glucose concentrations and enhancing the insulin level." (PMID 33747489, 2021). "The GHRKO mice also exhibit improved healthspan, showing improved cognition and insulin sensitivity, resistance to diabetes, reduced neoplasia, and decreased markers of aging such as adipose tissue (AT) senescence and mTORC1 signaling in liver, kidney, heart, and muscle." (PMID 34811874, 2021). "Our data demonstrated that the injection of non-diabetic plasma could be a promising therapeutic strategy to reverse diabetes-induced systemic inflammation and insulin resistance through inhibiting inflammatory cytokines." (PMID 34043673, 2021). "The ability to effectively provide telemedicine increases if a clinic has experience with diabetes technology provision (eg, insulin pumps, CGM sensors, electronic health records, diabetes management software, etc) and the required infrastructure (eg, software, computers, and internet connections)." (PMID 33571104, 2021). "Consistently, a decreased GLUT2 gene expression was observed in the pancreatic cells of experimental models of diabetes and an impaired insulin secretion and synthesis was observed in KO mice for GLUT-2, but, interestingly, these effects were restored when the GLUT-2 was expressed again." (PMID 34639123, 2021). "Of note, similar to diabetes, age-dependent sarcopenia may as well be viewed as a form of muscle-selective resistance to insulin." (PMID 34436453, 2021). "Besides, a potential role for melatonin in the relationship between circadian regulation of insulin secretion by the pancreatic islets and diabetes has been suggested." (PMID 34007273, 2021). "These compounds, due to their excellent properties of free radical scavengers, modulation of intracellular signaling pathways involved in glucose and insulin metabolism and anti-inflammatory properties, turn out to be an extremely attractive hope and future in the treatment of diabetes." (PMID 34443474, 2021). "However, this period of β-cell compensation leads to β-cell failure with secretion of insufficient insulin, and diabetes ensues." (PMID 34358068, 2021).
diabetes (continued). "The effect on mortality was even more pronounced in patients without a history of diabetes, and among patients with non‐insulin‐dependent diabetes who had never received insulin and carried a low‐risk cardiovascular profile." (PMID 33463901, 2021). "Interestingly, participants with diabetes treated with insulin showed a higher prevalence of phantom odours as compared with participants without diabetes (OR 2.98, 95% CI 1.41–6.32)." (PMID 34884338, 2021). "Our data support that AAC2 could serve as a new small molecule prototype for binding insulin and for the combinatorial treatment of diabetes and its complications." (PMID 35056977, 2021). "Multiple regression analysis showed that the PR and RI were positively correlated with age and diabetes duration (PR: P < 0.001, P = 0.03; RI: P < 0.001, P = 0.04, respectively), and PR was positively correlated with insulin use in type 2 diabetic patients (P = 0.002)." (PMID 34283877, 2021). "Rare neonatal forms of diabetes that develop within the first year of life are often caused by mutations in the KCNJ11 gene, which encodes a subunit of the pancreatic potassium channel that tightly regulates insulin secretion by beta cells." (PMID 33594477, 2021). "In summary, we concluded that the combination of enhanced dietary intakes and physical activity could alter the impact of the diabetes family history on insulin sensitivity." (PMID 33490287, 2021). "Diabetes is characterized by hyperglycemia, it refers to a complex disorder that involve profound alterations in the metabolism of fats, proteins and carbohydrates, resulting from defects in insulin secretion, insulin action, and even both of them." (PMID 33917300, 2021). "The reduced PAM-AMA in prevalent diabetes might go along with reduced insulin secretion, suggesting pancreatic β-cells as one source of circulating PAM." (PMID 34349173, 2021). "In 18 of 19 diabetes rats, the proportion of insulin+ cells varied from 0 to 15%." (PMID 33815287, 2021). "Trivalent chromium (Cr) and bitter melon (Momordica charantia L., BM) have been shown to independently interact with the insulin signaling pathway leading to improvements in the symptoms of insulin resistance and diabetes in some animal models and human subjects." (PMID 32488613, 2021). "The analysis of preoperative factors (age, diabetes duration, insulin use, HbA1c level, C-peptide level, and basal insulinemia) demonstrated that only a C-peptide level>3 ng/dL was a positive predictor (p=0.004) of late postoperative diabetes remission." (PMID 34378729, 2021). "In this study, obesity, sedentary activity, stress score, the interaction of diabetes duration with insulin use, serum creatinine level, age, occupation, and family history of hypertension were identified as independent determinants of hypertension among people with T2DM." (PMID 34424924, 2021). "Flexible insulin therapy gives the opportunity to patients with type 1 diabetes to use carbohydrate counting to adapt their insulin doses in order to refine their dietary freedom and their diabetes self - care skills." (PMID 34909088, 2021). "Diabetes mellitus is a heterogeneous and complex metabolic disorder characterized by hyperglycemia secondary to either resistance to insulin actions on the liver and peripheral tissues, insufficient insulin secretion from pancreatic β-cells, or both." (PMID 33842181, 2021). "In addition, several kinds of SGLT2 inhibitors are used in patients with type 1 diabetes mellitus as an adjuvant therapy to insulin." (PMID 33802741, 2021). "When combined with supervision from healthcare professionals (registered dietitian or Certified Diabetes Care and Education Specialist), carbohydrate counting has been used as the gold standard for determining insulin dosing for PWD to maintain glycemic control." (PMID 33918343, 2021). "This lack of insulin production or the failure of body cells to utilize it resulting in hyperglycaemia which is the hallmark of diabetes." (PMID 34422158, 2021).
diabetes (continued). "The value of insulin in the management of diabetes and the evidence in support of intensive insulin therapy targeting near-normalisation of glycaemic control to minimise the micro- and macrovascular complications of diabetes is overwhelming." (PMID 33738528, 2021). "The world's first Diabetes Medications (Insulin) was marketed in October 1923." (PMID 33850463, 2021). "Therefore, the data support an important role for insulin in controlling corneal epithelial cells’ homeostasis, with potential relevance in diabetes and wound healing." (PMID 33918477, 2021). "For the purpose of this analysis, metabolic deterioration of diabetes defines the condition in which patients with an established diagnosis of type 2 diabetes require the addition of insulin to oral antidiabetic therapy to maintain an acceptable metabolic control." (PMID 32978753, 2021). "Patients with shorter diabetes duration of T2D were more likely to experience insulin inertia." (PMID 34116645, 2021). "In type 1 diabetes (T1D), which accounts for approximately 10% of diabetes cases, an autoimmune response directed against pancreatic β-cells leads to a drastic loss of insulin-secreting cells and a near complete lack of the hormone." (PMID 34040585, 2021). "A previous report showed that participants without diabetes, but with a family history of diabetes, had a higher risk of glucose intolerance and lower insulin sensitivity." (PMID 34525777, 2021). "We hypothesized that combination of a TZD insulin sensitizer and the glucagon-like peptide-1 receptor agonist liraglutide would more significantly improve mouse models of diabetes and nonalcoholic steatohepatitis (NASH)." (PMID 34022222, 2021). "Both agents were capable of maintaining the animals under T1D conditions during the whole study without causing reversible diabetes or inducing insulin or glucose tolerance effects." (PMID 34712101, 2021). "Nrf2 activation can improve insulin sensitivity in a mouse model of diabetes." (PMID 34829566, 2021). "Overall, the results of this study illustrate the crucial role of defective insulin secretion and impaired insulin sensitivity in women with previous GDM who develop postpartum diabetes, and how genetic risk factors could be used to identify these women." (PMID 34801028, 2021). "Considering the status of diabetes, those who died had significant longer duration of the disease, increased proportion of treatment, and shift from oral anti-diabetic agent to additive insulin injection." (PMID 34823536, 2021). "The intervention effect of improvements in diabetes distress on glycemic control in peer support may be more pronounced among White and insulin-dependent veterans." (PMID 33427667, 2021). "Indeed, the use of continuous subcutaneous insulin infusion and continuous glucose monitoring systems have gained wide acceptance in diabetes care." (PMID 34249877, 2021). "As MSI-1436 was shown to protect against diabetes and enhance insulin sensitivity, we decided to unravel for the first time its effects on adipose tissue progenitor stem cells during control (standard culture medium, ND) and adipogenic (adipogenic differentiation medium, AD) conditions." (PMID 33536069, 2021). "Additionally, pancreatic islet transplantation can be superior to daily insulin therapy in delaying diabetes-related complications and in exerting overall metabolic control." (PMID 34589059, 2021). "Maturity Onset Diabetes in the Young (MODY) is caused by genetic defects of the pancreatic beta cells due to different genetic alterations, presented as autosomal dominant inherited disorders leading to a defect in insulin secretion." (PMID 33810048, 2021). "Diabetes mellitus (DM) is a disease in which the control of insulin levels has failed." (PMID 34768717, 2021).
diabetes (continued). "This review highlights the advantages of using α cells as a source for generating new β cells, the various investigative approaches to convert α cells into insulin-producing cells, and the future prospects and problems of this promising diabetes therapeutic strategy." (PMID 34882233, 2021). "The control of surgery-induced diabetes (type 3) requires insulin therapy." (PMID 34202998, 2021). "As a large animal model for mutant INS gene induced diabetes of youth (MIDY), we generated INSC94Y transgenic pigs, which are characterized by reduced body weight and β-cell mass, impaired insulin secretion with resulting hypoinsulinemia, and elevated blood glucose levels." (PMID 34888323, 2021). "Based on that, the purpose of this study was to evaluate the frequency of hypoglycemia and treatment satisfaction in patients with type 1 diabetes mellitus treated with insulin analogues after introduction of these drugs in the public health system in Southern Brazil." (PMID 33905628, 2021). "“Diabetes mellitus” is characterized by persistent hyperglycemia with disturbances of carbohydrate, fat, and protein metabolism resulting from defects in insulin secretion, insulin action, or both." (PMID 35127948, 2021). "Therefore, it is possible that surgeons were appropriately rejecting pancreases from donors treated with insulin in ICUs because they had diabetes." (PMID 33665687, 2021). "Type 2 diabetes mellitus (T2DM) is a highly prevalent metabolic disorder characterized by the imbalance in blood glucose level and altered lipid profile, which is caused by either disturbed insulin secretion, disturbed insulin effect, or usually both." (PMID 33850659, 2021). "Given the physiologic interrelationships between insulin sensitivity, insulin secretion, and insulin clearance, any analysis attempting to assess whether one of these is a predictor of diabetes must account for joint or confounding effects of the other two." (PMID 34206745, 2021). "A mechanism for 25(OH)D to exert effect on diabetes is that insulin secretion may be influenced by vitamin D indirectly with a vitamin D-dependent Ca-binding protein in pancreatic β cells." (PMID 33505536, 2021). "Type 1 diabetes mellitus (T1DM) results from autoimmune-mediated destruction of the insulin-producing β-cells, and thus, T1DM patients may require long term insulin treatment." (PMID 34577825, 2021). "In addition, in a 6-week hyperinsulinemic, euglycemic clamp study of 64 subjects with MAFLD and diabetes, the OCA was associated with improved insulin sensitivity." (PMID 34769060, 2021). "The difference in the prevalence of diabetes between the two birth cohorts could perhaps be explained by the improved survival since treatment with insulin began in the early 1920s." (PMID 34194845, 2021). "We recently showed that in patients with long-standing diabetes treated with insulin and older antidiabetic agents, endothelial function, elasticity, or arterial stiffness of large arteries failed to improve and cIMT deteriorated despite short-term aggressive glycemic control." (PMID 34940540, 2021). "Lastly, as vacor causes pancreatic β-cell destruction and diabetes in humans, these findings could also have broader implications, uncovering a role for SARM1 in the survival of insulin producing cells and aiding research on diabetes." (PMID 34870595, 2021). "This is especially important in the case of insulin, since long-term exposure to high concentrations of this hormone leads to insulin resistance, it was shown to be characteristic for type 2 diabetes mellitus, Alzheimer’s and Parkinson’s diseases and other endocrine pathologies." (PMID 34769198, 2021). "Diabetes is known as the silent killer, which occurs when the pancreas can no longer make insulin or the body cells don't appropriately respond to the produced insulin." (PMID 33563291, 2021). "Diabetes patients suffer from a lack of control over glucose metabolism caused by insulin insufficiency." (PMID 34287337, 2021).